TERT (telomerase reverse transcriptase)
Diseases named in the same sentence as TERT in open-access papers (continued):
Sharing a sentence is not in itself a finding about the gene and the disease.
thyroid cancer (continued). "Two recurrent TERT (telomerase reverse transcriptase) promoter mutations, C228T and C250T, have been reported in thyroid carcinomas and were correlated with high-risk clinicopathological features and a worse prognosis." (PMID 33776938, 2021). "In thyroid cancer however, TERT promoter mutation was associated with increased overall mutation burden (medianTERT-wt = 0.32 mut/Mbp vs. medianTERT-mut = 0.82 mut/Mbp, U-test p = 7.9 × 10−8)." (PMID 32859912, 2020). "Further, regulation includes the allele-specific regulation of the TERT promoter in thyroid cancer cells harboring the TERT promoter mutation." (PMID 32849278, 2020). "The presence of the TERT promoter mutation is indicative of worse clinicopathological factors in thyroid cancer." (PMID 32849278, 2020). "The association between telomerase reverse transcriptase (TERT) promoter mutations and some clinical behaviors in thyroid cancer remains controversial and requires additional investigation." (PMID 31655978, 2020). "In fact, the incidence of TERT mutations we observed in T4 well differentiated thyroid cancers was like that reported in poorly differentiated and anaplastic thyroid carcinomas." (PMID 32415114, 2020). "The two parts of this oncogenic duet (BRAFV600E and mutated TERT promoter) have been shown to work cooperatively together to promote oncogenesis, leading to aggressive thyroid cancer phenotype." (PMID 32751138, 2020). "Compared to early-stage WDTC, co-occurrence of BRAF and TERT mutations are common in locally advanced (T4) thyroid cancer and are associated with an increased risk of recurrence." (PMID 32415114, 2020). "Several previous studies have examined the role of the promoter mutations in the TERT gene (C228T and C250T) in thyroid cancer." (PMID 31758407, 2020). "It seems that TERT mRNA expression is also associated with worse prognosis features in thyroid cancer, similar to the presence of TERTp mutations, as advanced in previous reports." (PMID 32659948, 2020). "Another difference in the molecular profile of T4 tumors as compared to the control cohort with T1/T2 tumors was that TERT mutations were observed in over half as compared to less than 10% of lower stage thyroid cancers (p < 0.05)." (PMID 32415114, 2020). "Recent studies have reported the feasibility of TERT promoter mutation detection and its applicability in screening programs for patients with thyroid cancer to predict patient's outcome." (PMID 32850388, 2020). "There is a building body of evidence that co-mutations of BRAF/TERT signify a highly aggressive form of thyroid cancer that is more likely to recur." (PMID 32415114, 2020). "Activating point mutations in the TERT promoter markedly activate TERT transcription and are associated with epigenetic alterations observed in thyroid cancer cell lines and patient tumors." (PMID 32849278, 2020). "Two promoter mutations, 228C>T and 250C>T in TERT gene have shown a significant role in the pathogenesis of thyroid cancer, with 228C>T as the most frequently occurring compared to the 250C>T." (PMID 33247684, 2020). "Generally, presence of a TERT promoter mutation leads to a definite diagnose of thyroid cancer, although a rare case of TERT promoter mutation was previously reported in a benign follicular adenoma that occurred concurrently with other mutations." (PMID 32976686, 2020). "We therefore looked for associations between SNV burden with CTNNB1 mutation in hepatocellular cancer, and with TERT promoter mutation in thyroid cancer." (PMID 32859912, 2020). "Of the 50 thyroid nodule cases, BRAF, NRAS, and TERT promoter mutation correctly detected thyroid cancer respectively in 12, 7, and 5 cases from 39 malignancy cases." (PMID 33247684, 2020). "TERT promoter mutations have been associated with aggressive tumor behaviors and worse prognosis in thyroid cancer." (PMID 32393293, 2020).
thyroid cancer (continued). "TERT mutation had a significantly higher prevalence in aggressive thyroid cancer and served as an independent predictor of persistent disease and mortality for differentiated thyroid cancer." (PMID 33392186, 2020). "The recently identified TERT promoter mutations are also recognized as a clinically important diagnostic marker for thyroid cancer." (PMID 33247684, 2020). "TERTp mutations and TERT mRNA expression are correlated with worse prognosis features in malignant thyroid tumours, whereas TERT mRNA expression in the benign tumours is associated with the presence of thyroiditis." (PMID 32659948, 2020). "TERT promoter mutations are generally found only in aggressive thyroid cancer, with the frequency ranging from 4.7% to 25.5%." (PMID 33247684, 2020). "TERT expression in follicular cell derived thyroid carcinomas has similar associations as the TERTp mutations, the highest levels of expression being found in aggressive histotypes, larger size of tumours, and from older patients." (PMID 32659948, 2020). "The aim of this study was to determine the utility of digital PCR technique in detecting BRAFV600E and TERT promoter mutations (C228T and C250T) in thyroid cancer tissue samples." (PMID 31810221, 2019). "The BRAF V600E and TERT promoter mutations (C228T and C250T) have been extensively related to prognosis in thyroid cancer." (PMID 30884810, 2019). "Two hotspot mutations in the TERT promoter region, c.‐124C > T (C228T) and c.‐146C > T (C250T), occur in various cancer types including thyroid cancer." (PMID 31408918, 2019). "Two mutually exclusive TERT promoter mutations are recurrent in thyroid cancer, one at position -124 (c228t) and one at position -146 (c250t) upstream of the TERT translation start site." (PMID 31540307, 2019). "The aim of this study was to search for novel TERT promoter mutations and additional mechanisms of TERT activation in thyroid cancer." (PMID 31408918, 2019). "Given the utility in knowing the status of BRAFV600E and TERT mutations in thyroid cancer, different methods have been used to access the mutation status." (PMID 31810221, 2019). "Novel alterations in TERT promoter, including single‐nucleotide variants and duplications, lead to increased TERT promoter activity, highlighting additional mechanisms of TERT activation in thyroid cancer." (PMID 31408918, 2019). "Our previous studies have widely demonstrated that the promoter mutation of TERT was significantly correlated with aggressiveness and recurrence in thyroid cancer." (PMID 31024447, 2019). "Mutations in the TERT promoter were recently reported to correlate strongly with aggressiveness in advanced forms of thyroid cancer." (PMID 31482953, 2019). "This picture is consistent with previous reports in adult series: in thyroid carcinoma, TERT promoter mutations are associated with more aggressive histopathological features and a worse prognosis." (PMID 31456750, 2019). "First reported in 2013, TERT promoter mutation (C228T and C250T) in thyroid cancer has progressed rapidly in recent 5 years." (PMID 30619082, 2018). "Many studies have demonstrated TERT mutation was associated with more aggressive clinicopathological features of thyroid cancer, such as male gender, ETE, LNM, advanced stage, distant metastasis, recurrence, and mortality." (PMID 30619082, 2018). "In the pooled data, we found thyroid cancer were more likely to recur in patients with TERT promoter mutations according to the meta-analysis." (PMID 30024548, 2018). "Telomerase reverse transcriptase (TERT) promoter mutations have been described in different pathological types of thyroid cancers (TC)." (PMID 30024548, 2018). "So that, in pediatric thyroid cancers, the value of TERT promoter mutations as a single measure to identify malignant tumors from benign ones is also limited." (PMID 30024548, 2018).
thyroid cancer (continued). "As well, mutations in the TERT promoter were described to occur with high frequency and to be associated with aggressiveness in different types of cancers including thyroid cancers." (PMID 29416733, 2018). "Since TERT promoter mutations were first found in thyroid cancer, it has become a hotspot of TC research." (PMID 30024548, 2018). "Recent studies have shown that approximately 10% of PTCs have a TERT gene mutation, whereas 40% of poorly differentiated thyroid cancers and 70% of ATCs have a TERT mutation." (PMID 29163356, 2017). "TERT promoter mutations therefore have potential as novel diagnostic and prognostic markers in the setting of thyroid cancer." (PMID 29085338, 2017). "According to previous reports, TERT promoter mutation has been demonstrated to be particularly prevalent in the aggressive thyroid cancers PDTC and ATC." (PMID 28423545, 2017). "TERT promoter mutations have recently been described in thyroid cancers deriving from follicular cells, occurring in 11% of PTC, 17% of FTC, 43% of PDTC, and 40% of ATC." (PMID 29085338, 2017). "The promoter mutation variant C228T in TERT, which was recently reported as another distinct biomarker for advanced thyroid cancer, was also identified in 4 samples from 3 patients (2 ATC patients and one HVPTC patient)." (PMID 28423545, 2017). "Recently, two TERT promoter mutations, −124 C > T (C228T) and −146 C > T (C250T), have been detected in thyroid cancer cell lines and tissues including well differentiated, poorly differentiated and anaplastic thyroid carcinomas." (PMID 28423545, 2017). "Novel molecular-based management strategies, such as RET-PTC, RAS, BRAF (V600E), and TERT mutations for thyroid nodules and thyroid cancer are the most exciting developments in thyroid-cancer medicine." (PMID 29100371, 2017). "In their study, they found TERT promoter mutations in 0% (0/179) of benign thyroid nodules and 7.0% (9/129) of differentiated thyroid cancers, representing 100% diagnostic specificity." (PMID 29312581, 2017). "In thyroid cancers, TERT promoter mutations were predominantly found in aggressive disease, such as tall cell variant PTC, widely invasive follicular thyroid carcinoma, poorly differentiated carcinoma, and anaplastic carcinoma." (PMID 29312581, 2017). "For example, a mutation in the telomerase reverse transcriptase (TERT) promoter is an independent indicator of poor prognosis for all differentiated thyroid carcinomas." (PMID 29108240, 2017). "These recent findings on TERT promoter mutations in thyroid cancer are exciting, but they remain to be confirmed and generalized by further and high-power studies, ideally in different ethnic populations." (PMID 26943032, 2016). "We found that TERT promoter mutations are prevalent in aggressive thyroid cancers and are associated with distant metastasis of WDTCs in Korean patients with a high prevalence of the BRAF V600E mutation." (PMID 26857243, 2016). "In thyroid cancers, TERT promoter mutations were predominantly found in more aggressive disease, such as tall cell variant PTC, widely invasive follicular thyroid carcinoma (FTC), poorly differentiated carcinoma, and anaplastic carcinoma." (PMID 26857243, 2016). "Recent studies have reported TERT promoter mutations in thyroid cancers; these mutations are particularly prevalent in aggressive thyroid cancers and BRAF mutation-positive PTC." (PMID 27064992, 2016). "The same results were obtained when the TERT probe was mutated to contain the C228T or C250T variants that are found in thyroid cancer." (PMID 27852061, 2016). "Co-regulation of TERT suggests a mechanism by which allelic variants in/near FOXE1 are associated with thyroid cancer risk." (PMID 27852061, 2016).
thyroid cancer (continued). "A number of additional investigations revealed a significant correlation between the presence of TERT promoter mutations and relapse in thyroid cancer." (PMID 27438857, 2016). "Our study and 13 articles were included for the meta-analysis of TERT promoter mutation prevalence in various thyroid cancers." (PMID 26857243, 2016). "We report for the first time the clinical impact of TERT promoter mutations on thyroid cancers that occur in a BRAF V600E prevalent area." (PMID 26857243, 2016). "BRAF V600E and TERT promoter mutations can activate the mitogen-activated protein kinase (MAPK) signaling pathway in thyroid cancer." (PMID 26857243, 2016). "Somatic mutations in the promoter of the TERT (Telomerase Reverse Transcriptase) gene have been described as highly recurrent in different types of cancer including thyroid cancer." (PMID 25214840, 2014). "TERT promoter mutations are detected in approximately 10% of thyroid cancer cases." (PMID 40363930, 2025). "However, it has been shown that there is a very low concordance in BRAF, KRAS, NRAS and TERT promoter mutations between primary or metastatic thyroid tissues and plasma ctDNAs in early stage thyroid cancer patients." (PMID 40095491, 2025). "Moreover, TERT promoter mutations have been found in several other thyroid cancer subtypes, such as FTC, poorly differentiated thyroid carcinoma (PDTC), and ATC." (PMID 40940966, 2025). "The TERT promoter mutation in thyroid cancer is linked to more aggressive clinical outcomes." (PMID 40988283, 2025). "Mutations in the TERT promoter are significant findings in the context of thyroid carcinoma." (PMID 39744583, 2025). "Further research could offer valuable insights into the mechanisms underlying the circRNA-mediated regulation of TERT in thyroid cancers." (PMID 38316961, 2024). "TERT promoter mutation often co-exists with BRAF or RAS mutation in thyroid cancer." (PMID 39235852, 2024). "Researching the molecular effects of TERT promoter mutations may have therapeutic applications in addition to improving thyroid cancer diagnosis and prognostication." (PMID 38501105, 2024). "TERT is overexpressed in thyroid cancer and associated with poor prognosis of PTC." (PMID 38313800, 2024). "TERT promoter mutation analysis may eventually be included into standard clinical practice, which could improve the accuracy of managing thyroid cancer and open up new possibilities for individualized treatment plans." (PMID 38501105, 2024). "Notably, in thyroid cancer, TERT promoter mutations enhance telomerase activity, leading to immortalization of cancer cells." (PMID 38495498, 2024). "In addition, Yang et al44 showed that TERT mutant thyroid cancers were linked to a higher occurrence of distant metastasis at the time of diagnosis." (PMID 37462445, 2024). "TERT promoter mutation is accompanied by enhanced telomerase reverse transcriptase activity and increased invasion potential in tumor cells, which tremendously affect the malignancy and prognosis of thyroid cancer." (PMID 38277563, 2024). "Additionally, TERT promoter mutations are among the most recognized markers associated with aggressive thyroid cancer phenotypes." (PMID 36909304, 2023). "We considered that anaplastic thyroid cancer (ATC), an extremely aggressive form of thyroid cancer with a high incidence of TERT promoter mutations, may arise from well differentiated thyroid cancer." (PMID 37772080, 2023). "Notably, TERT promoter mutations in thyroid cancer have been associated with aggressive clinical behavior." (PMID 36984536, 2023). "In multivariable Cox regression analysis with interaction model, AAD ≥ 55 and TERT promoter mutation showed significantly increased HRs, revalidating the results of previous studies that have emphasized the importance of TERT promoter mutation as a robust prognostic marker in thyroid cancers." (PMID 37948420, 2023).
thyroid cancer (continued). "An example is telomerase reverse transcriptase (TERT), a key determinant of the enzymatic activity of telomerase, whose mutation was found to be related to numerous cancers, such as breast, bladder, prostate, and thyroid cancers." (PMID 37894396, 2023). "Indeed, among the 13 thyroid cancer cases with TERT promoter mutations, 5 cases subsequently underwent targeted next-generation sequencing at the request of the clinician." (PMID 36984536, 2023). "The present study aimed to examine whether concurrent mutations with TERT promoter mutations are associated with more aggressive thyroid cancers compared to TERT promoter mutations alone." (PMID 36672362, 2023). "Thyroid cancer patients with a high probability of harboring TERT promoter mutations can thus be screened for confirmative TERT promoter mutation testing, such as real-time PCR or next-generation sequencing, which can ultimately reduce the medical costs shouldered by them." (PMID 36984536, 2023). "We hypothesized that the presence of any other molecular alterations, hence the accumulation of mutations during carcinogenesis, would influence the aggressiveness of thyroid cancer with TERT promoter mutations." (PMID 36672362, 2023). "We mainly performed PCR testing for TERT promoter mutations in thyroid cancer cases presenting with large tumor sizes showing aggressive behavior, which might lead to selection bias." (PMID 36984536, 2023). "Similarly, increased TERT gene copy number and upregulation of telomerase have been identified in breast cancer, thyroid carcinoma, and lung adenocarcinoma in association with poor prognosis." (PMID 38033865, 2023). "To refine the prognostic value of TERT‐expression‐related alterations in thyroid cancer, we analysed the methylation and mutation status of TERT promoter in the whole series (n = 106) by next‐generation‐sequencing and determined TERT‐locus copy number for a subset of 31 tumours by SNP‐array." (PMID 35979662, 2022). "Genetic alterations such as BRAF and TERT mutations can also affect the survival rate of thyroid cancer patients Ferroptosis, a recently discovered type of programmed cell death, appears to play a critical role in carcinogenesis and cancer therapy efficacy, according to mounting data." (PMID 35741758, 2022). "Thus, we harmonized the WHO 2017 classification and TERT promoter mutations, which are promising molecular prognostic markers, and re-classified the thyroid carcinomas into three alternative groups." (PMID 34497362, 2022). "The presence of TERT mutation was associated with worse prognosis in breast cancer, thyroid carcinoma, and lung adenocarcinoma, meanwhile, TERT promoter mutations are highly associated with sarcomatoid histology in patients with metastatic pleural mesothelioma and urothelial carcinomas." (PMID 36741696, 2022). "Although studies from different countries and geographical regions around the world have consistently found TERT promoter mutations in thyroid cancers and provided evidence of their role in thyroid cancer progression, the prevalence of TERT mutations varies considerably." (PMID 33776938, 2021). "The TERT gene mutation was frequently observed in thyroid cancer brain metastases." (PMID 33915699, 2021). "Investigations of clinical thyroid cancer patients have revealed that TERT promoter mutation is highly correlated with advanced or progressive disease, including advanced tumor stages, extrathyroidal extension, vascular invasion, lymph node metastases, distant metastases, and recurrence." (PMID 33669363, 2021).